EFNA5 (ephrin A5)
Description:
Cell surface GPI-bound ligand for Eph receptors, a family of receptor tyrosine kinases which are crucial for migration, repulsion and adhesion during neuronal, vascular and epithelial development. Binds promiscuously Eph receptors residing on adjacent cells, leading to contact-dependent bidirectional signaling into neighboring cells. The signaling pathway downstream of the receptor is referred to as forward signaling while the signaling pathway downstream of the ephrin ligand is referred to as reverse signaling. Induces compartmentalized signaling within a caveolae-like membrane microdomain when bound to the extracellular domain of its cognate receptor. This signaling event requires the activity of the Fyn tyrosine kinase. Activates the EPHA3 receptor to regulate cell-cell adhesion and cytoskeletal organization. With the receptor EPHA2 may regulate lens fiber cells shape and interactions and be important for lens transparency maintenance. May function actively to stimulate axon fasciculation. The interaction of EFNA5 with EPHA5 also mediates communication between pancreatic islet cells to regulate glucose-stimulated insulin secretion. Cognate/functional ligand for EPHA7, their interaction regulates brain development modulating cell-cell adhesion and repulsion.
Synonyms: EPLG7; LERK7; AF1; EFL5; GLC1M; RAGS
Tractability: Antibody: UniProt places it where antibodies can reach, with high confidence; its Gene Ontology location is reachable by antibodies, with high confidence; UniProt predicts a signal peptide or a membrane-spanning region.
Gene: Protein-coding gene on chromosome 5 (107,376,894 to 107,670,937, reverse strand). Ensembl gene ENSG00000184349.
Subcellular location: Cell membrane; Membrane, caveola
Subcellular location (Human Protein Atlas): Cytosol; Vesicles
Pathways (Reactome):
Developmental Biology: EPH-Ephrin signaling; EPH-ephrin mediated repulsion of cells; EPHA-mediated growth cone collapse
Gene Ontology:
Molecular function: ephrin receptor binding; protein binding; receptor ligand activity; neurotrophin TRKA receptor binding; neurotrophin TRKB receptor binding; neurotrophin TRKC receptor binding; transmembrane receptor protein tyrosine kinase activator activity; chemorepellent activity
Biological process: apoptotic process; ephrin receptor signaling pathway; negative regulation of substrate adhesion-dependent cell spreading; regulation of actin cytoskeleton organization; regulation of cell morphogenesis; regulation of cell-cell adhesion; regulation of focal adhesion assembly; regulation of microtubule cytoskeleton organization; axon guidance; axonal fasciculation; lens fiber cell morphogenesis; positive regulation of insulin secretion involved in cellular response to glucose stimulus; positive regulation of phosphatidylinositol 3-kinase/protein kinase B signal transduction; cell communication; collateral sprouting; negative chemotaxis; positive regulation of collateral sprouting; positive regulation of synapse assembly; signaling; synaptic membrane adhesion
Cellular component: external side of plasma membrane; plasma membrane; adherens junction; basement membrane; caveola; cell periphery; GABA-ergic synapse; membrane
Genetic constraint (gnomAD): Loss-of-function variants: 3 observed, 16.3 expected, observed/expected ratio (o/e) 0.18, 90% interval 0.083 to 0.48. The upper end of that interval is the gene's LOEUF score, 0.48, which puts it in group 2 of 6, group 1 being the genes least tolerant of losing a copy. Missense variants: 203 observed, 257.33 expected, observed/expected ratio (o/e) 0.79, 90% interval 0.7 to 0.89. Synonymous variants: 104 observed, 101.54 expected, observed/expected ratio (o/e) 1.02, 90% interval 0.87 to 1.21.
Homologues: Orthologues: chimpanzee EFNA5 (100% identical), guinea pig EFNA5 (100% identical), macaque EFNA5 (99% identical), mouse Efna5 (99% identical), pig EFNA5 (99% identical), rabbit EFNA5 (98% identical), dog EFNA5 (98% identical), tropical clawed frog efna5 (89% identical), rat Efna5 (86% identical), zebrafish efna5a (63% identical), Caenorhabditis elegans efn-4 (26% identical), Caenorhabditis elegans efn-2 (25% identical), and 4 more. Paralogues in human: EFNA2 (46% identical), EFNA3 (38% identical), EFNA1 (37% identical), EFNA4 (35% identical), EFNB1 (24% identical), EFNB2 (24% identical), EFNB3 (22% identical).
Diseases named in the same sentence as EFNA5 in open-access papers:
EFNA5 is named in the same sentence as 81 diseases in open-access papers, as found by Europe PMC text mining. Sharing a sentence is not in itself a finding about the gene and the disease. The quoted sentences say what the papers report.
prostate carcinoma (11 papers, 2014 to 2024). A carcinoma that arises from epithelial cells of the prostate gland. "High EFNA5 expression is associated with lower OS in ovarian carcinoma and pancreatic cancer but associated with a better prognosis in prostate cancer, hepatoma, and glioblastoma." (PMID 35945523, 2022). "Moreover, an association between the mRNA level of EFNA5 and DNA methylation of its promoter were documented for ccRCC, chRCC, pRCC, mesothelioma, prostate cancer, thymoma, and diffuse large B-cell lymphoma." (PMID 36497462, 2022). "Cell-to-cell contact of prostate cancer cells through the EphA-ephrin-A interaction suppressed stomatin expression, while knockdown of EphA3/7 or ephrin-A5 increased stomatin expression." (PMID 39377541, 2024). "The similar ephrin-A5 content in serum of the patients with prostate cancer and BPH indicates that serum ephrin-A5 cannot be used as a marker of common prostate malignancy." (PMID 35551177, 2022). "Regarding the function of EFNA5, recent studies have shown its significant expression alterations in prostate cancer, gastric cancer and colorectal cancer compared to conventional normal tissues." (PMID 32666642, 2020). "Increased levels of ephrin-A5 in LNCaP cell culture media after androgen exposure suggests androgen-induced release of ephrin-A5 from prostate cancer cells." (PMID 29682554, 2018). "ADAM10 contributes to prostate cancer metastasis via cleaving ephrin-A5." (PMID 36922678, 2023). "Our finding that ephrin-A5 is disassociated from EphA3 and released outside the cell by ADAM10 suggests that ephrin-A5 may have certain diagnostic value in prostate cancer metastasis." (PMID 35551177, 2022). "The EFNA5 gene plays a role in several cancers, including ovarian cancer and prostate cancer." (PMID 36139405, 2022). "Additionally, an independent retrospective study on metastatic castration-resistant prostate cancer has reported a correlation of lower serum levels of ephrin-A5 with shorter survival time." (PMID 29682554, 2018). "EFNA5 (Ephrin A5) showed significantly higher expression in prostate tumors than in normal prostate tissue, and might plays an important role in the development of prostate cancer." (PMID 30791942, 2019).
cataract (10 papers, 2008 to 2024). Partial or complete opacity of the crystalline lens of one or both eyes that decreases visual acuity and eventually results in blindness. "In human patients, mutations of the EPHA2 gene cause congenital and age-related cataracts, while polymorphisms of the EFNA5 gene, which encodes the ephrin-A5 protein, are linked to age-related cataracts." (PMID 36291158, 2022). "In C57BL/6J background mice, ephrin-A5−/− lenses displayed anterior polar cataracts caused by abnormal proliferation of anterior epithelial cells undergoing epithelial-to-mesenchymal (EMT) transition." (PMID 35295853, 2022). "Our work and other recent studies show that loss of EphA2 or ephrin-A5 in the lens can causes cataracts and abnormal cell membranes, cytoskeletal networks, and fiber cell morphologies." (PMID 34899394, 2021). "Complementing these observations, our previous study identified that the loss of ephrin-A5 also leads to cataracts in mice, indicating that EphA2 serves as a receptor for the ligand in maintaining the clarity of the crystalline lens." (PMID 22570727, 2012). "Our previous studies showed that ephrin-A5 acts as a ligand for EphA2 in the lens, and the loss of ephrin-A5 function leads to cataracts in mice." (PMID 22570727, 2012). "These clustered mesenchymal cells migrate into fiber cell layers at the anterior suture area to cause anterior cataracts in ephrin-A5(-/-) lenses." (PMID 22140528, 2011). "Recently, it was demonstrated that ephrin-A5 acts as a regulator for EPHA2, and loss of ephrin-A5 function can lead to cataracts in mice." (PMID 20361013, 2010). "Ephrin-A5 (Efna5) knockout lenses develop anterior polar cataracts due to disruption of cell-cell adhesion via E-cadherin and β-catenin mislocalization leading to epithelial-to-mesenchymal transition (EMT) in anterior epithelial cells." (PMID 38984128, 2024). "While there are anterior epithelial cell defects and cataracts in C57BL/6J background ephrin-A5−/− lenses, severe fiber cell defects are more obvious in mixed (129/Sv:C57BL/6) background KO mice." (PMID 35295853, 2022). "Based on these studies, genetic background strongly influences cataract phenotype and severity in ephrin-A5−/− mice." (PMID 35295853, 2022). "Together, this evidence suggests that the cataracts observed in ephrin-A5−/− mice occur independently of CP49." (PMID 23401654, 2013). "EphA2−/− mice develop congenital cataracts in a manner similar to ephrin-A5−/− mice, developing subcapsular vacuoles leading to lens opacity and rupture." (PMID 23401654, 2013). "As a follow-up to our previous study on the cataracts observed in ephrin-A5−/− animals, we have further examined the morphological and molecular changes in the ephrin-A5−/− lens." (PMID 23401654, 2013). "We and others have shown previously that the ligand ephrin-A5 and receptor EphA2 both play critical roles in normal lens function, as both ephrin-A5−/− and EphA2−/− mice develop cataracts." (PMID 23401654, 2013). "To follow up our former study, we have further investigated the function of ephrin-A5 in the lens by identifying its expression during development and determining the spatial and temporal changes that lead to cataracts in ephrin-A5−/− mice." (PMID 23401654, 2013). "Ephrin-A5−/− animals have noticeable lens deficits as early as P6 and become opaque by P21, while EphA2−/− animals develop lens deficits at 1 month of age and cataracts by 5 months." (PMID 23401654, 2013). "Ephrin-A5 knockout (-/-) mice often display anterior polar cataracts while EphA2(-/-) lenses show very mild cortical or nuclear cataracts at weaning age." (PMID 22140528, 2011). "Recent studies report that ephrin-A5 knockout (-/-) mice develop cataracts with variable severity and incomplete penetrance, and EphA2 mutations lead to age-dependent cortical cataracts in humans and mice." (PMID 22140528, 2011).
cataract (continued). "Thus, it is unlikely that the significant increase in EphA2-pS898 level in lens epithelial cells from 8-month-old ephrin-A5-/- mice activates EMT in anterior epithelial cells to form cataracts." (PMID 39466050, 2024). "We therefore analyzed whether the status of CP49 affected the formation of cataracts in ephrin-A5−/− mice." (PMID 23401654, 2013). "Moreover, postnatal day 21 (P21) ephrin-A5(-/-) mice often developed anterior cataracts with mild opacities at the anterior polar region." (PMID 22140528, 2011). "Significant differences in lens phenotypes of mouse models with disrupted EphA2 or ephrin-A5 signaling indicate that genetic modifiers likely affect cataract phenotypes and progression, suggesting a possible reason for the variability of human cataracts due to Eph-ephrin dysfunction." (PMID 35295853, 2022). "Thus, we also tested whether there were any GJ conductance changes in lenses from 12-month-old control, ephrin-A5–/– and EphA2–/– mice to determine whether GJ conductance changes could account for the age-related cataracts in EphA2–/– lenses." (PMID 34899394, 2021). "Recent studies have identified the Eph receptor ligand ephrin-A5 as a major contributor to lens development, as mice lacking ephrin-A5 develop abnormal lenses, resulting in cataracts." (PMID 23401654, 2013). "Recently, however, it has been reported that mice lacking ephrin-A5, a ligand of Epha2, develop cataracts as a result of impaired lens fiber cell adhesion." (PMID 19005574, 2008). "The cataracts in the ephrin-A5−/− mutants occur regardless of the presence of the CP49 mutation." (PMID 23401654, 2013). "Our own observations have found that regardless of the status of CP49, ephrin-A5−/− mice under this mixed background still develop cataracts indicating that the CP49 protein may not directly affect the cataracts observed in ephrin-A5−/− mutants." (PMID 23401654, 2013).
Stroke (9 papers, 2014 to 2022). Sudden impairment of blood flow to a part of the brain due to occlusion or rupture of an artery to the brain. "In stroke, ephrin-A5 upregulation in reactive astrocytes is associated with a significant increase in the phosphorylation of EphA receptors in peri-infarct tissue and EphB1 levels are increased during axonal sprouting following stroke." (PMID 26928051, 2016). "In adult models of stroke, the use of ephrin-A5 antagonists, GABAα5 inverse agonists, histone deacetylase 5 inhibitors, or C-C chemokine receptor 5 (CCR5) knockdown at delayed time points augmented motor recovery." (PMID 34659399, 2021). "One particular EphA4 ligand, ephrin-A5 (efnA5), is of specific interest since its expression is increased in reactive astrocytes after stroke, resulting in reduced growth of cortical axonal projections during recovery." (PMID 31300041, 2019). "We selected efnA5 as target ligand, since in another neuronal injury model, stroke, evidence exists for upregulation of efnA5 in astrocytes, which reduced axonal regeneration after injury." (PMID 31300041, 2019). "This high astrocytic ephrin-A5 expression inhibited axonal sprouting and motor recovery after stroke." (PMID 28526745, 2017). "EFNA5 is reported to be upregulated in reactive astrocytes following stroke, which limits axonal sprouting from cortical neurons and motor recovery." (PMID 25069764, 2014). "Blocking efnA5 signalling improved the recovery of mice after stroke injury." (PMID 31300041, 2019). "In contrast to a stroke model, EfnA5 was minimally expressed in astrocytes." (PMID 31300041, 2019). "This upregulation of efnA5 in reactive astrocytes was not only induced after experimental stroke, but also by physical stress as shown in vitro, suggesting that efnA5 might be upregulated in astrocytes under stressful conditions." (PMID 31300041, 2019). "It has already been shown that targeting ephrin-A5, a molecule which is expressed by reactive astrocytes in the peri-infarct region, improves recovery after stroke in mice, and that currently used antidepressant drugs act by rescuing astrocytic defects, such as d-serine decrease." (PMID 28212850, 2018). "For example, ephrin-A5 expressed by RAs in the peri-infarction region can inhibit axon regeneration, and inhibition of ephrin-A5 in the peri-infarction area can promote axon growth on day seven after stroke, which provides a long treatment time window so that has broad clinical prospects." (PMID 35321205, 2022).
ovarian carcinoma (7 papers, 2019 to 2024). A malignant neoplasm originating from the surface ovarian epithelium. "A majority of earlier studies focused on the role of Efna5 in developmental biology, especially the nervous system, or in several types of cancers, such as ovarian cancer and osteosarcoma." (PMID 33102589, 2020). "As a target gene of miR-454-3p, EFNA5 is an important component of axon guidance pathway and has been recognized as promising prognostic biomarker and therapeutic target for ovarian cancer." (PMID 31664600, 2019). "Moreover, four neural genes (NTN1, UNC5B, EFNB2, and EFNA5) were nominated as promising biomarkers and therapeutic targets in ovarian cancer patients." (PMID 39456618, 2024). "EFNA5 is also a possible therapeutic target in ovarian cancer." (PMID 35309935, 2022). "Using ovarian cancer tissue microarrays and longitudinally collected patient cells, we show here that ephrinA5/EFNA5 is specifically overexpressed in the most aggressive high-grade serous carcinoma (HGSC) subtype, and increased in the HGSC cells upon disease progression." (PMID 33893375, 2021).
breast carcinoma (6 papers, 2016 to 2022). "EFNA4 regulates stem cell properties in glioma, whereas EFNA5 regulates the phenotype of breast cancer stem cell-like cells." (PMID 35945523, 2022). "Bioassay studies demonstrated that EFNA1, EFNA3, and EFNA4 expression were higher in breast cancer than in normal tissues, while EFNA5 showed an opposite trend." (PMID 35309935, 2022). "In the UALCAN database, the mRNA expression of EPHA1, EPHA10, EFNA1, EFNA3, and EFNA4 was significantly higher, whereas that of EPHA2, EPHA4, EPHA5, and EFNA5 was significantly lower in breast cancer tissues than in paracancerous tissues." (PMID 33977106, 2021). "In addition, modulating the nanoscale spacing of ephrin-A5 dimers to direct EphA2 receptors at defined positions using DNA origami nanostructures tuned receptor phosphorylation levels in human breast cancer MDA-MB-231 cells, resulting in reduced cell invasion." (PMID 32352518, 2020). "Here, we use ephrin-A5-decorated DNA origami nanostructures (ephrin-A5 DNA nanocalipers) to form ligand nanoassemblies with well-defined spatial organizations, which tune EphA2 phosphorylation in human GBM and breast cancer cells and also downstream signaling in GBM." (PMID 32352518, 2020).
Age-related cataract (5 papers, 2011 to 2024). A type of cataract (opacification of the lens) that forms during the course of aging. "Mutations in the EPHA2 (encodes for the receptor EphA2) and EFNA5 (encodes for the ligand ephrin-A5) genes have been linked to congenital and age-related cataracts in human patients." (PMID 39466050, 2024). "Non-synonymous single nucleotide polymorphisms (nsSNPs) in the EFNA5 gene, which encodes the ephrin-A5 protein, have also been reported to cause age-related cataracts in humans." (PMID 35295853, 2022). "In particular, dysfunction of the receptor EphA2 or the ligand ephrin-A5 lead to a variety of congenital and age-related cataracts, defined as any opacity in the lens, in human patients." (PMID 35295853, 2022). "Recent studies have revealed that disruption of Eph-ephrin signaling, in particular the receptor EphA2 and the ligand ephrin-A5, in humans and mice lead to congenital and age-related cataracts." (PMID 34899394, 2021). "Ephrin-A5(-/-) and EphA2(-/-) mice, maintained mainly in the C57BL/6J strain background with wild-type Bfsp2 (or CP49) genes, develop congenital or age-related cataracts with incomplete genetic penetrance that is consistent with previous reports." (PMID 22140528, 2011).
glioblastoma (5 papers, 2017 to 2022). The most malignant astrocytic tumor (WHO grade IV). "At the protein level, EFNA5 was downregulated in glioblastoma multiforme and ccRCC, but highly expressed in endometrial carcinoma." (PMID 36497462, 2022). "Integrated transcriptomic and epigenomic analyses of glioblastoma initiating cells (GIC) in a mouse model uncovered a novel epigenetic regulation of EfnA5." (PMID 31988455, 2020). "Using RNA-seq, we determined the transcriptional profiles of human glioblastoma cells treated with DNA nanocalipers presenting a single ephrin-A5 dimer or two dimers spaced 14, 40 or 100 nm apart." (PMID 32352518, 2020).